IL6 (interleukin 6)
Diseases named in the same sentence as IL6 in open-access papers (continued):
Sharing a sentence is not in itself a finding about the gene and the disease.
Insulin resistance (continued). "Obese subjects included in the intervention study presented insulin resistance (higher HOMA-IR index) and low grade inflammation (high serum IL-6 and hsCRP concentration) whereas baseline blood Gla-OC, Glu-OC, and total osteocalcin levels were lower than in non-obese controls." (PMID 30388806, 2018). "Similarly, in the present study, bovine α-LAH not only exhibits protective effects against HFD induced insulin resistance, but also significantly downregulated inflammation-related gene (MCP-1, TNF-α and IL-6) expression in epididymal adipose tissues." (PMID 29473848, 2018). "Moreover, we did not assess insulin resistance markers, such as homeostasis model assessment of insulin resistance, and inflammatory markers (MIF, TNF-α, and IL-6)." (PMID 30563254, 2018). "Although insulin resistance represented by the HOMA index was associated with anthropometric variables and with serum leptin, adiponectin, chemerin, and IL-6 concentrations, in our study, no statistically significant relations with PTC staging were identified." (PMID 30627158, 2018). "Our results showed that bovine α-LAH supplementation improved systemic and adipose insulin resistance, downregulated TNF-α, IL-6, and MCP-1 mRNA expression and suppressed IKKα/β and MAPK signaling pathways in adipose tissues of obese C57BL/6J mice induced by HFD." (PMID 29473848, 2018). "According to their physiological role, they have been divided into two groups: insulin resistance inducting factors such as resistin, tumor necrosis factor alpha (TNF-α), and interleukin 6 (IL-6) and insulin-sensitizing factors such as leptin, adiponectin, and visfatin." (PMID 29593647, 2018). "In addition to TNFα, several other pro-inflammatory cytokines are increased in obesity and contribute to the development and/or exacerbation of insulin resistance, including monocyte chemoattractant protein-1 (MCP1), interleukin-1 (IL-1), and IL-6." (PMID 29570618, 2018). "Adipocytokines such as leptin, adiponectin, resistin, interleukin-6 (IL-6) and tumor necrosis factor-α (TNF-α) are mediators produced by adipocytes which have important roles in the pathophysiology of insulin resistance, inflammation, hypertension, endothelial dysfunction and atherosclerosis." (PMID 28747175, 2017). "Some pro-inflammatory cytokines synthesized by lymphocytes and keratinocytes in psoriatic skin, including IL-6, IL-17 and TNF-alpha, may contribute to systemic insulin resistance, a common feature of NAFLD." (PMID 28905102, 2017). "The connection between WNT5A expression in VAT and IL-6/CRP levels is of particular relevance, given the large body of clinical evidence that links increased IL-6 signaling and/or increased circulating CRP levels to insulin resistance, diabetes and atherosclerotic CVD4,40–43." (PMID 29229927, 2017). "Fasting blood samples were collected for assessment of nonesterified fatty acids, tumor necrosis factor-α (TNF-α), interleukin-6 (IL-6), adiponectin, insulin and estimation of insulin resistance (HOMA-IR)." (PMID 28977210, 2017). "A prospective study looking at Mg intake and incidence of diabetes, systemic inflammation, and insulin resistance in young American adults followed up for 20 years (n = 4497) showed a significant inverse relationship with Mg intake and hs-CRP, IL-6, fibrinogen, and HOMA-IR." (PMID 29093983, 2017). "Furthermore, we observed significant production of IL-6 and MCP-1 in a coculture compared to the effect in macrophage cells; these two molecules are related to macrophage infiltration and insulin resistance in adipose tissue." (PMID 28348560, 2017). "An animal study showed that BBR reduced blood TNF-α, IL-6, and MCP-1 levels of JNK and IKKβ phosphorylation in obese mice fed with a high-fat diet, as well as indicated that BBR improves insulin resistance possibly through inhibiting the activation of macrophages in adipose tissue." (PMID 29164155, 2017).
Insulin resistance (continued). "Therefore, elevated IL-6 and TNF-α serum levels can lead to insulin resistance and the occurrence of sarcopenia." (PMID 28701179, 2017). "RBPP-P attenuated the contents of TNF-α and IL-6 in HFD-fed mice adipose tissues, indicating that it decreased fat mass and improved insulin resistance, which may be related to the regulation of inflammation." (PMID 28452943, 2017). "Furthermore, melatonin attenuates the secretion of pro inflammatory cytokines such as interleukin-6 (IL-6), tumor necrosis factor (TNF)-α, interferon (IFN)-gamma under insulin resistance condition in high fat diet mouse." (PMID 28764741, 2017). "High levels of inflammatory mediators, such as tumor necrosis factor alpha (TNF-α), interleukin 6 (IL-6), and C-reactive protein (CRP), might contribute to an increase in insulin resistance." (PMID 28403353, 2017). "The frequencies of IL-6-producing T cells were not correlated with the values of insulin resistance index HOMA-IR (homeostatic model assessment of insulin resistance), perhaps because HOMA-IR calculation includes fasting insulin levels." (PMID 26918832, 2016). "In line with the observed decreased de novo lipogenesis, improved hepatic insulin resistance, and reduced TAG accumulation in ω3 compared with ω6-PUFA fed mice, hepatic Il-6 expression as well as the protein level of the proinflammatory nuclear factor, NFκB, was diminished in ω3-PUFA fed mice." (PMID 27999451, 2016). "In addition, IL-6 and TNF-α promote insulin resistance in skeletal muscle and liver as well as proinflammatory activity in synovial tissue." (PMID 27964760, 2016). "Furthermore, elevated blood levels of IL-6 have been observed in patients with NAFLD, and it is thought that IL-6 can induce insulin resistance and inflammation in the liver." (PMID 27046197, 2016). "Thus, we could speculate that the effects of the IL-6 system on frailty, especially sarcopenia, may involve their contribution to lean body mass decrease, bone mineral density decrease, anemia, thrombocytosis, cholesterol and albumin decrease, insulin resistance, and cognitive impairment." (PMID 27119508, 2016). "Additionally, increased circulating IL-6 levels stimulate the hypothalamic-pituitary-adrenal (HPA) axis, which plays an important role in control of central obesity, hypertension, insulin resistance, and PCOS." (PMID 26942201, 2016). "Elevated IL-6 levels may contribute to disease development, by increasing the expression of cytokines like TNF-α known to induce insulin resistance, or by inducing insulin resistance itself." (PMID 26244048, 2015). "Similarly to TNFα, both IL-6 and MCP-1 are critically involved in insulin resistance and chronic inflammation." (PMID 25685071, 2015). "Furthermore, the homeostasis model assessment of insulin resistance (HOMA-IR) index and serum proinflammatory cytokine levels (TNF-α and IL-6) involved in dyslipidaemia was markedly improved." (PMID 26264374, 2015). "HTS also reduces steatosis, insulin resistance, and IL-6 levels in patients with non-alcohol fatty liver disease." (PMID 26296204, 2015). "Our findings showed that CLE effectively decreased the production of inflammatory mediators, such as IL-6, TNF-α, and FFA in db/db mice, which could be due to decreased HOMA-IR and insulin, constantly improving insulin resistance in target tissues." (PMID 25889508, 2015). "After further adjustments for interleukin-6 and insulin resistance, central FM, waist circumference and sarcopenia were no longer significantly associated with SCI." (PMID 26692280, 2015). "TNF-α or IL-6 downregulated insulin-stimulated glucose uptake and consumption in three types of cell lines, and casein injection decreased glucose and insulin tolerance in C57BL/6J mice, indicating that the inflammatory stress promoted insulin resistance." (PMID 26449763, 2015). "OA attenuated insulin resistance and decreased the levels of TNF-α and IL-6." (PMID 26843885, 2015).
Insulin resistance (continued). "Additionally, diabetes is associated with high levels of blood cytokines including IL-1β, IL-6, IL-12, IL-17, IL-18, TNF-α and IFN-γ, which mediate the physiological adaption of insulin production and insulin resistance." (PMID 26684748, 2015). "Moreover, a number of the genes such as proinflammatory genes of TNFα, IL6 and COCS3, which were increased in the muscle of hypertensive DS rats, have been shown to play a fundamental role in the pathogenesis of insulin resistance and T2DM." (PMID 25928697, 2015). "However, an intravenous treatment with 600mg of ALA for two weeks in obese patients with glucose intolerance resulted in improvement of insulin resistance, decreased levels of free fatty acids, LDL-cholesterol as well oxidized LDL, TNF α and IL-6." (PMID 25104975, 2014). "Moreover, IL-6 and TNF-α increase expression of SOCS in the liver which is involved in increased hepatic SREBP-1c expression and insulin resistance." (PMID 24733068, 2014). "The adipokines IL-6 and TNF-α are related to insulin resistance." (PMID 24465964, 2014). "Adipose tissue macrophage infiltration and inflammatory response are often associated with an obesity phenotype, where enlarged adipocytes release free fatty acids through lipolysis and pro-inflammatory cytokines TNFα, IL-6 and MCP-1, resulting in development of insulin resistance." (PMID 25195639, 2014). "In addition, IL-6 appears to be directly involved in the activation of NF-kB/STAT-3 and insulin resistance." (PMID 25338520, 2014). "Together, the data in both human and mouse show that MAP3K8 is involved in local adipose tissue inflammation, specifically for IL-1β and its responsive cytokines IL-6 and IL-8, but does not seem to have systemic effects on insulin resistance." (PMID 24586913, 2014). "Moreover, ablation of Fas (CD95), a further member of the tumor necrosis factor receptor (TNFR)-superfamily, in murine adipocytes has a similar positive effect on insulin resistance during HFD as demonstrated for TNFα and IL-6." (PMID 24897026, 2014). "Among these inflammatory cytokines, the evidence that insulin resistance is linked to TNF-α, but not IL-6 and IL-8, is well established." (PMID 25202741, 2014). "In vivo release of interleukin-6 (IL-6), linked closely to hs-CRP pathway, but not tumor necrosis factor-α (TNF-α), which is related to insulin resistance, has been reported in human subcutaneous adipose tissue (SAT)." (PMID 23326306, 2013). "Finally, resistin has been demonstrated to stimulate the secretion of several inflammatory factors (e.g., TNF-α, IL-6, IL-8, and MCP-1) known to play a role in the induction of insulin resistance." (PMID 24455420, 2013). "An increase of IL-6 (p = 0.015) and TNF (from 49.7 to 53 pg/mL), and a decrease of plasma APO (7658–5152 ng/ml, respectively) were noted after hemihepatectomy, the surgery also resulted in exacerbation of insulin resistance evaluated by HOMA index (p = 0.007)." (PMID 22829443, 2013). "Curcumin improved peripheral insulin resistance in insulin-resistant ob/ob mice with steatosis by reducing NF-κB/RelA DNA-binding activity, decreasing mRNA level of TNF and IL-6, and enhancing IL-4 production in hepatic TNF/iNOS-producing dendritic cells and adipose tissue macrophages." (PMID 24348712, 2013). "Similarly, IL-6 and TNF-α have been shown to suppress insulin signaling and GLUT-4 receptor expression in skeletal muscle, both of which result in insulin resistance." (PMID 23826335, 2013). "It was reported that NF-κB results in insulin resistance by activating proinflammatory cytokines like TNF-α, IL-6, IL-1β, and resistin, which consequently activates the c-Jun N-terminal kinase (JNK) and NF-κB pathways to create a vicious cycle that exacerbates tissue damage." (PMID 24348717, 2013). "The reductions in DAS28-CRP, CRP and IL-6 levels were independent of improvement in insulin resistance." (PMID 24020899, 2013).
Insulin resistance (continued). "Our present study revealed that Lr263 administration markedly suppressed the increased TNF-α and IL-6 production by adipose tissue in HFD rats, suggesting that Lr263 ameliorated insulin resistance through reducing oxidative stress as well as proinflammatory cytokines production." (PMID 23590862, 2013). "Of note, elevated levels of TNFα, IL-1β, IL-6 and IL-10 mRNA in MO with high insulin resistance degree were not statistically different from the levels found in T2D-MO." (PMID 23110196, 2012). "Furthermore, TNF-α can stimulate the production of other cytokines and chemokines, such as IL-6 and Monocyte Chemoattractant Protein 1 (MCP1), which can induce insulin resistance." (PMID 22816003, 2012). "In one study with breast cancer patients, IL-6 and estrogen levels were found to be higher in the insulin-resistant breast cancer patients without treatment compared to the ones without insulin resistance." (PMID 22701472, 2012). "In addition, interleukin (IL)-6, IL-8, monocyte chemotactic protein (MCP)-1, and tumor necrosis factor (TNF-α) have also been found to be increased with elevated insulin resistance along with factors such as serum amyloid A, resistin, leptin, and adiponectin." (PMID 23091306, 2012). "In analogy, elevated IL-1, IL-6, and TNF-α levels in septic patients may contribute to insulin resistance." (PMID 22272381, 2012). "Additionally, the inflammatory kinase I-kappa-B kinase-β (Ikκβ) contributes to insulin resistance by activating NF-κB and induces production of various inflammatory cytokines, including TNF-α and IL-6." (PMID 23213270, 2012). "The association with insulin resistance was partly independent of body fat, but was not related to proinflammatory cytokines TNF-a, IL-6, or MCP-1." (PMID 22984471, 2012). "It is important to note that the protection from insulin resistance reported for SCD1 transgenic mice is associated with increased GLUT4 translocation; however, neither plasma concentrations nor tissue expression of IL-6 were reported in these studies." (PMID 23209931, 2012). "Both IL-6 and TNF may inhibit the transcription of IRS-1 and glucose transporter (GLUT)-4 genes, thus reducing glucose transport and enhancing insulin resistance in obese patients." (PMID 22691241, 2012). "IL-6 is responsible for stimulating hepatocytes to secrete C reactive protein and has been proposed to be responsible for the systemic consequences of COPD (insulin resistance, osteoporosis, muscle degradation, and depression)." (PMID 21267454, 2011). "Adipose tissue secrete IL-6 and TNF-α during insulin resistance, and high levels of TNF-α and IL-6 may downregulate the expression of adiponectin." (PMID 22144985, 2011). "Inflammatory cytokines such as TNF, IL-6 and MCP-1 have been also shown to inhibit insulin action through modification of signaling properties of insulin receptor substrates, contributing to liver and skeletal muscle insulin resistance." (PMID 21789167, 2011). "The relationship between central obesity and insulin resistance could be explained based on the metabolism of free fatty acids or other adipocytokines (TNF-α, IL-6, adiponectin) released from the visceral fat." (PMID 22025967, 2011). "Moreover, in cultured cells, tissues and whole animals, NF-κB has been shown to activate TNFα, IL6, IL-1β, and plasminogen activator inhibitor 1 (PAI-1) inducing insulin resistance." (PMID 20508722, 2010). "However, adiponectin secretion is known to be influenced by factors that induce insulin resistance, which include tumor necrosis factor (TNF)-α, interleukin (IL)-6, C-reactive protein (CRP), lipid metabolism, diet and exercise habits." (PMID 18507868, 2008). "Overexpression of resistin increased the levels of three proinflammatory cytokines, tumor necrosis factor alpha (TNFα), interleukin 6 (IL-6) and monocyte chemoattractant protein-1 (MCP-1), which play important roles for insulin resistance, glucose and lipid metabolisms during adipogenesis." (PMID 16854242, 2006).
Insulin resistance (continued). "Insulin resistance and another inflammatory state, atherosclerosis, share similar pathophysiological mechanisms, mainly due to the actions of the two major proinflammatory cytokines, TNF-alpha and IL-6." (PMID 17140429, 2006). "Hypersecretion of IL-6 and TNFα may exert major stimulatory effects on the synthesis of acute-phase proteins such as PAI-1, which is also related to insulin resistance." (PMID 16787541, 2006). "However, we did observe that circulating CRP levels were positively related to body weight, visceral fat mass, and insulin resistance, while IL-6 and TNF-alpha were not related to any metabolic marker." (PMID 40218888, 2025). "Furthermore, a diet high in fatty acids, has been suggested to induce hepatic insulin resistance, resulting in increases in plasma TNF-α and IL-6, in apo-CIII-overexpressing mice, with an increase in apo-CIII playing a major role in liver inflammation and cell death in patients with MASLD." (PMID 39941760, 2025). "Mechanistically, increased TSH levels in subclinical hypothyroidism promoted the secretion of cytokines IL-1α, IL-1β and IL-6 by inducing macrophage M1 polarization, which upregulated EGR1 to transcriptionally activate LCN2 and SOCS3 in insulin target cells, thereby exacerbating insulin resistance." (PMID 40523992, 2025). "Considering that pro-inflammatory cytokines are also key contributors to the development of insulin resistance, the compensative increase in GDF-15 levels in response to IL-6 elevation might counteract this phenomenon, with a potential impact on clinical outcomes." (PMID 40283592, 2025). "The underlying mechanisms may involve multiple pathways: Firstly, insulin resistance induced by elevated TyG levels promotes macrophage polarization toward a pro-inflammatory phenotype, leading to the release of cytokines such as TNF-α and IL-6." (PMID 41024162, 2025). "In obese PCOS, the altered inflammatory milieu—driven by TNF-α, IL-6, and resistin—can induce the release of EVs enriched with pro-inflammatory microRNAs that disrupt IRS phosphorylation, impede GLUT4 translocation, and modify FOXO1-mediated transcription, thereby exacerbating insulin resistance." (PMID 41010046, 2025). "Insulin resistance has been mainly related to high-fat and high-carbohydrate diets leading to fat mass gain in overweight and hence often related to obesity, particularly visceral fat accumulation, which leads to the release of pro-inflammatory cytokines like TNF-α, IL-6, and resistin." (PMID 40136728, 2025). "Furthermore, it has been observed that individuals with diabetes exhibit increased levels of pro-inflammatory cytokines, such as interleukin-6 (IL-6) and tumor necrosis factor-α (TNF-α), which contribute to chronic inflammation, exacerbating pancreatic β-cell damage and insulin resistance." (PMID 40917351, 2025). "The findings from this study, particularly the differentiation between PCOS patients with and without insulin resistance, underscore the critical role of IL-6 as an inflammatory mediator and highlight the multifactorial aspects inherent in the pathophysiology of PCOS." (PMID 40226143, 2025). "Excess adiposity contributes to insulin resistance through increased free fatty acid flux, ectopic fat deposition, and chronic low-grade inflammation driven by adipokines and pro-inflammatory cytokines such as tumour necrosis factor-alpha (TNF-α) and interleukin-6 (IL-6)." (PMID 41395632, 2025). "Moreover, exercise-induced secretion of interleukin-6 (IL-6) from muscle cells has anti-inflammatory effects by inhibiting cytokines like tumor necrosis factor alpha (TNF-α) and interleukin-1 beta (IL-1β), contributing to reduced insulin resistance." (PMID 41008394, 2025). "According to a previous study, the alleviation of insulin resistance (hyperglycemia and hyperinsulinemia) by dietary cholest-5-en-3-one is attributable to a decrease in the production of inflammatory cytokines, such as Ccl2 (MCP-1) and Il6 (IL-6), in the adipose tissues." (PMID 38921456, 2024).